ACE3P (angiotensin I converting enzyme 3, pseudogene)
Synonyms: ACE3
Gene: Unitary pseudogene on chromosome 17 (63,507,056 to 63,519,806, forward strand). Ensembl gene ENSG00000224353.
Diseases named in the same sentence as ACE3P in open-access papers:
ACE3P is named in the same sentence as 3 diseases in open-access papers, as found by Europe PMC text mining. Sharing a sentence is not in itself a finding about the gene and the disease.
ACE3P shares sentences with these, for which no sentence is quoted: Infertility (2 papers); COVID-19 (1); Hyperglycemia (1).